GSK3B (glycogen synthase kinase 3 beta)
Diseases named in the same sentence as GSK3B in open-access papers (continued):
Sharing a sentence is not in itself a finding about the gene and the disease.
neurodegenerative disease (continued). "Indeed, the specific GSK3β inhibitor has emerged as a therapeutic target for drug development for tau pathology in neurodegenerative disease, our studies thus broaden the theoretical basis for the treatment of neurodegenerative diseases with GSK3β inhibitors." (PMID 32575075, 2020). "Thus, inhibition of GSK-3β has been found to be beneficial and provide a potential therapeutic target for neurodegenerative diseases." (PMID 32714487, 2020). "However, the effect of α-syn overexpression on GSK-3β activity and the role of the GSK-3β/β-catenin signaling pathway in neurodegenerative diseases are still unclear." (PMID 32879633, 2020). "This synergic effect between tau, αSyn, and GSK-3β may be involved in the pathophysiology of several neurodegenerative diseases that show the accumulation of both tau and αSyn." (PMID 32560668, 2020). "It has also been suggested that DFO's effects in neurodegenerative disease models may be related to its inhibition of glycogen synthase kinase (GSK‐3β), a proline‐directed serine/threonine kinase." (PMID 31960628, 2020). "Since α‐synuclein not only maintains normal synaptic function but also plays an important role in the degenerative diseases of the nervous system, it is presumed that GSK3β plays a pivotal role in the maintenance of synaptic function and in neurodegenerative diseases." (PMID 31429527, 2019). "Current studies on GSK-3β enzyme inhibitors focus on the treatment of neurodegenerative diseases." (PMID 30965670, 2019). "Indeed, reducing tau hyperphosphorylation through a specific kinase (e.g. GSK3β) inhibition has emerged as a therapeutic target for drug development for tau pathology in neurodegenerative disease." (PMID 30466464, 2018). "In addition to its known involvement of glycometabolism, GSK3β is involved in neuronal growth, neuro-proliferation, differentiation and apoptosis in neurodegenerative diseases." (PMID 29515352, 2018). "Furthermore, a previous study has shown that LiCl mediates the reductions in GSK3β, tau phosphorylation, and cell death in neurodegenerative diseases." (PMID 30513908, 2018). "By activating GSK-3β and JNK, the endoplasmic reticulum stress can induce caspase-12-dependent apoptosis, which has been implicated in a broad range of human diseases, including neurodegenerative diseases, cancer, diabetes, and vascular disorders." (PMID 29137141, 2017). "We propose that the PGC‐1α response to changes in GSK3β function may be important in aging and neurodegenerative disease." (PMID 26521867, 2016). "Therefore, the development of molecules that can block the molecular interaction between α-Syn and GSK-3β is necessary for devising effective therapeutics for neurodegenerative diseases that result from tau hyperphosphorylation." (PMID 25977830, 2015). "While in neurodegenerative disease GSK3β-mediated phosphorylation of tau results in neuronal degradation, in paclitaxel-induced neurotoxicity, a reduction in microtubule stabilization may be beneficial to axonal integrity." (PMID 25535399, 2014). "This hypothesis provides the basis for the development of GSK-3β inhibitors as potential therapeutic drugs for treating AD and other neurodegenerative diseases." (PMID 18958152, 2008). "In the context of neurodegenerative disease due to impaired autophagy, this suggests that GSK3β may help to promote autophagy not only through the activation of ULK1, but also through preserving levels of transcription factors like TFEB that lead to the upregulation of autophagy-promoting genes." (PMID 37443837, 2023). "Therefore, inhibiting the PI3K/mTOR/GSK3β pathway may be an effective treatment for neurodegenerative diseases." (PMID 32832542, 2020). "In summary, our results demonstrate that the overexpression of GSK-3β in neurons only in adult animals and not during development reproduces the histopathological marks of AD, as well as the cognitive deficit associated with this neurodegenerative disease." (PMID 33013321, 2020).
neurodegenerative disease (continued). "Furthermore, increased insulin-like growth factor receptor (IGF-1R) protein levels and an activation of the phosphatidylinositol 3-kinase/Akt/glycogen synthase kinase 3 beta/β-catenin signaling pathway were identified in a mouse neurodegenerative disease model." (PMID 30406034, 2018). "While GSK3β is activated in many of these neurodegenerative diseases, it may not elicit the same outcome since PS1 mutation caused GSK3β activation but led to increased ER-mitochondria tethering." (PMID 28852477, 2017). "Since GSK-3β is also strongly implicated in AD and PD 75, 76, alterations to GSK-3β activity may be a common mechanism for disrupting the VAPB–PTPIP51 tethers and ER–mitochondria associations in at least some forms of neurodegenerative disease." (PMID 26899735, 2016). "In addition, some CAMs have been shown to shuttle between FA and nucleus to regulate gene expression, including CDK5, ERK, GSK3B and COPS5 (JAB1) and members of the LIM family of proteins (PXN and Trip6), many of which have been implicated in the molecular pathology of neurodegenerative diseases." (PMID 22815752, 2012). "Dysregulation of the PI3K/AKT/GSK3β signaling pathway provokes brain insulin resistance (BIR), neuroinflammation, and neuronal apoptosis, the hallmarks of PD and other neurodegenerative diseases." (PMID 40474025, 2025). "The immunoreactivity of GSK-3β and phosphorylated GSK-3β is found to be increased in neuronal tissues with age, and further investigation of this will provide insights regarding GSK-3β-related neurodegenerative diseases." (PMID 40148800, 2025). "The selective GSK3β inhibitor TDZD-8 has been used in trials to evaluate its effects on cognition and neuroprotection in neurodegenerative disease patients." (PMID 41190025, 2025). "Tideglusib, a non-ATP competitive inhibitor of GSK3β, originally developed for neurodegenerative diseases, exhibits renoprotective effects in DKD models by reducing podocyte damage and oxidative stress through GSK3β modulation." (PMID 40526103, 2025). "Many signaling involved in the regulation of GSK3β such as Wnt/β-catenin and PI3K are disturbed in neurodegenerative disease." (PMID 39719518, 2024). "Ningalins act as potent inhibitors against the HIV-1 virus and kinases related with neurodegenerative diseases (CDK5, GSK3b, CD1d)." (PMID 36662210, 2022). "Once again, we have correlated treatment with DFO and modulation of the HIF‐1α and GSK‐3β pathways, which have been postulated to play an integral role in DFO's effects in animal models of brain injury and neurodegenerative disease." (PMID 31960628, 2020). "Compound 65 inhibited CK1, CDK5, GSK3β and SW620 (3.1 μM), KB-3-1 (2.0 μM), which are targets for treating neurodegenerative diseases." (PMID 31450856, 2019). "GSK-3β, one of two GSK-3 isoforms, is known to play critical roles in oxidative stress-induced neuronal apoptosis and the pathogenesis of neurodegenerative diseases." (PMID 30301204, 2018). "Notably, in that study RCAN1 facilitative activity was switched on by nuclear export of GSK-3β, indicating that targeting the factors involved in this inhibitory mechanism of GSK-3β-mediated NFAT nuclear export may have a therapeutic potential in neurodegenerative diseases." (PMID 27597899, 2016). "Accordingly, our results show the importance of continuing studies to determine the pathophysiological roles of GSK-3β and TRPM2 in neurodegenerative diseases." (PMID 22188973, 2011). "Of the two closely related isoforms, GSK-3α and GSK-3β, GSK-3β is known to play critical roles in oxidative stress-induced neuronal apoptosis and pathogenesis of neurodegenerative diseases." (PMID 19430525, 2009). "Drawing a parallel to the activation of GSK3β and CDK5 in neurodegenerative diseases, particularly the hyperphosphorylation of tau in AD, it is plausible that synphilin-1 may also undergo hyperphosphorylation in PD." (PMID 40869369, 2025).
neurodegenerative disease (continued). "Thus, one possibility is that some neurodegenerative disease insults including familial mutant TDP43, FUS, C9orf72 derived toxic DPRs and Tau activate GSK3β which phosphorylates VAPB and/or PTPIP51 to disrupt their binding." (PMID 40045432, 2025). "Since GSK-3β has a critical role in metabolism, insulin signaling, protein regulation, and inflammation, GSK-3β inhibition is regarded as an attractive target for therapeutic intervention in metabolic and neurodegenerative diseases." (PMID 38367137, 2024). "It is regarded as a non-ATP competitive inhibitor of GSK-3β used in different neurodegenerative diseases." (PMID 38367137, 2024). "In addition, they also show potent inhibition against kinases related with neurodegenerative diseases, such as cyclic-dependent kinase 5 (CDK5), glycogen synthase kinase 3b (GSK3b) and casein kinase I (CD1d)." (PMID 36662210, 2022). "Unlike Akt, GSK-3β is active in resting, unstimulated cells, and aberrant activation of GSK-3β is implicated in aging and neurodegenerative diseases." (PMID 34012501, 2021). "Little is known about the link between AKT/GSK‐3β and NRF2 in neurodegenerative diseases." (PMID 29997171, 2018). "Thus, we reveal GSK‐3β inhibition as a new therapeutic strategy in X‐ALD, which is currently under investigation for other neurodegenerative diseases." (PMID 29997171, 2018). "Furthermore, oxidative stress increases the levels of phosphorylated tau protein, GSK3β, BACE1, and Aβ in neurodegenerative diseases." (PMID 26635562, 2015). "Similarly, targeting GSK3β to restore Beclin-1 expression and LC3B-II conversion in neuronal models may offer a translatable strategy for neurodegenerative diseases, where impaired autophagic flux is a major pathological driver." (PMID 41190025, 2025). "Thus, the beneficial effects of UDCA in FTD/ALS and other neurodegenerative diseases may involve at least in part, correction to damaged VAPB-PTPIP51 tethering and ER-mitochondria signaling via inhibition of GSK3β." (PMID 38395965, 2024). "Therefore, it would be necessary to modulate the excessive activity of GSK-3β in response to pathological condition in neurodegenerative diseases without inhibiting physiological roles of GSK-3β." (PMID 35055183, 2022). "Excessive activation of GSK-3β has negative effects in neurodegenerative diseases." (PMID 35055183, 2022). "However, the PKA/GSKIP/GSK3β axis and the PKA and GSK3 signaling pathways involved in the pathogenesis of neurodegenerative disease events remain unclear." (PMID 31640277, 2019). "Thus, there appears to be different routes by which neurodegenerative disease insults can impact upon ER–mitochondria tethering via the VAPB–PTPIP51 interaction, some involving activation of GSK-3β and some such as we describe here for α-synuclein, involving binding to the tethering proteins." (PMID 28337542, 2017).
infection (87 papers, 2005 to 2026). The state of being infected such as from the introduction of a foreign agent such as serum, vaccine, antigenic substance or organism. "Intracellularly, β-catenin activation and Wnt target gene expression is linked to activation of PI3K and Akt which inhibit GSK3β during infection, but the role of the Wnt receptor complex protein LRP6 in this mechanism remains to be investigated." (PMID 31681283, 2019). "Various studies have confirmed that GSK3β regulates the response to infections caused by Gram (−)/(+) bacteria like Helicobacter pylori, Francisella tularensis, and Mycobacterium sp." (PMID 29434603, 2018). "BMVEC were transduced at a multiplicity of infection (MOI) of 0.1 with replication-deficient adenoviruses encoding the previously characterized GSK3β S9A and GSK3β KM mutants." (PMID 23418486, 2013). "Knowledge of glycogen synthase kinase 3β (GSK3β) activity and the molecules identified that regulate its function in infections caused by pathogenic microorganisms is crucial to understanding how the intensity of the inflammatory response can be controlled in the course of infections." (PMID 34017345, 2021). "Further experiments will be needed to determine whether GSK-3β can be modulated to influence susceptibility to infection in chickens." (PMID 26664916, 2014). "Contrarily, p-GSK-3β protein level was found to be maximum at 8 h post-infection (3.4-fold increase compared with uninfected control, P < 0.0001)." (PMID 41277868, 2026). "Salmonella infection has been reported to reduce the phosphorylation of GSK-3β (Ser9) in mouse colonic epithelial cells within 6 h post-infection." (PMID 41413615, 2025). "Infection with H. pylori ΔvacA significantly reduced phosphorylation of Ser129 α-Syn, and c-Abl at both autophosphorylation sites (Y412 and Y245), and slightly affects pY216 GSK3β as compared to infection with H. pylori WT." (PMID 40988055, 2025). "Similar to our results, when S. typhimurium infected colon epithelial cells, GSK3β-dependent β-catenin degradation was upregulated, which suppressed the Wnt-β-catenin pathway to facilitate the pathogen infection." (PMID 40865802, 2025). "Both the AKT and GSK3β inhibitors were able to suppress inflammation in all infection conditions, indicating that those are feasible targets for quorum-sensing-dependent suppression." (PMID 39975246, 2025). "The expression of GSK-3β in ESCC tissues is high, and its expression is proportional to the infection time of P. gingivalis, which indicates that P. gingivalis induces the high expression of GSK-3β in ESCC cells in a time-dependent manner." (PMID 40843171, 2025). "We focused on the effect of P-4423632 and GSK3β CRISPR KO on host macrophage signaling during infection with WT Mtb and Mtb ΔptpA mutant." (PMID 39175770, 2024). "Treatment with P-4423632 resulted in upregulation of apoptosis and CRISPR-KO of GSK3β in THP-1 cells increased apoptosis in response to infection with Mtb." (PMID 39175770, 2024). "In another laboratory experiment, Tat infection of murine neurons resulted in a GSK-3-β activity increase." (PMID 36790601, 2023). "We next studied the effects of targeting ER stress/PKA/GSK-3β-dependent Wnt/β-catenin signaling with either PKA activity or ER stress inhibitors on inhibition of the infection of infectious extracellular HCV." (PMID 37158967, 2023). "This infection led to upregulation of GSK-3β level and reduction in the active β-catenin protein level, which subsequently reduce the level of cyclin-D1." (PMID 37861335, 2023). "Key genes including elongation initiation factor pathway genes, GSK3B, and regulatory associated protein of mTOR (RPTOR) genes that protect cells from infection were significantly downregulated in Native Hawaiians." (PMID 36450776, 2022). "Using the dsRNA marker, screening against HCoV-229E and SARS-CoV-2 demonstrated that targeting GSK3β resulted in effective viral control in 31% and 19% of the compounds (≥ 50% infection inhibition), respectively." (PMID 36508083, 2022).
infection (continued). "Studies have shown that GBS achieves ascending infection by inducing glycogen synthase kinase 3β(GSK3β) phosphorylation." (PMID 35090514, 2022). "In this study, we screened a GSK3β-focused library of inhibitors in a cellular infection model and identified several potent candidates active against human coronavirus HCoV-229E and SARS-CoV-2." (PMID 36508083, 2022). "Building on existing knowledge regarding the involvement of GSK3β in infection progression, we aimed to identify compounds active against this key human kinase as potential coronaviridae inhibitors." (PMID 36508083, 2022). "Similar to results found using our laboratory strain, in vitro infection with the clinical isolates resulted in increased protein levels of p-GSK-3β (Ser9) and p-β-catenin (Ser33/37/Thr41) over the time course of infection." (PMID 34749529, 2021). "LiCl, a GSK3 inhibitor used as a reference inhibitor in this experiment, inhibited GSK3β and reduced the production of pro-inflammatory cytokines during infection." (PMID 33803419, 2021). "GSK3β signaling promoted by infection, activated NF-κB-mediated expression of proinflammatory molecules and inhibited the activity of β-catenin, Nrf2, CREB, STAT1/3, and cJun-AP1, except in MCF7 and MDA-MB-231 stimulated with LPS." (PMID 34017345, 2021). "During infections, GSK3β regulates the production of several pro-inflammatory cytokines while suppressing the production of anti-inflammatory cytokines." (PMID 33803419, 2021). "HCE cells expressing GS3-HPSE exhibited significantly greater levels of phosphorylation of Akt and GSK-3β than cells transfected with empty vector (EV) or proenzyme HPSE in the presence of infection." (PMID 34749529, 2021). "We had previously reported that PAN stimulation and SGK3 shRNA infection of podocytes significantly decreased the phosphorylation of GSK3β, and the SGK3/GSK3β signaling pathway inhibited podocin expression during PAN-induced podocyte injury." (PMID 35126185, 2021). "We have also included articles in which inflammation was reduced by modulation of GSK3β activity during infection with bacteria, viruses and parasites or PAMPs stimulation." (PMID 34017345, 2021). "Nevertheless, a broad spectrum of GSK3β inhibitors as well as other inhibitors have been reported to inhibit GSK3β and inflammation during infection with bacteria, viruses and parasites as well as LPS and PGN cell stimulation." (PMID 34017345, 2021). "Dysregulation of GSK3β during infection can result in overwhelming production of pro-inflammatory cytokines." (PMID 33803419, 2021). "Infection of WT, GSK3α−/−, or GSK3β−/− cells with WT Salmonella resulted in a similar amount of Y705-phosphorylated STAT3, which was no longer detected in lysates from GSK3α/β−/− cells, despite similar total STAT3 levels." (PMID 31862381, 2020). "The expression of GSK3β was up-regulated by BPIV3 infection, and suppressed by LiCl as a specific inhibitor of GSK3β." (PMID 32127006, 2020). "In infections caused by Dengue virus (DENV), GSK3β regulates transcription factor NF-κB,leading to production of nitric oxide (NO) and induction of apoptosis." (PMID 32130369, 2020). "An inhibitory phosphorylation of GSK3β-Ser9 was observed in Huh7 cellsafter 1 min of infection with DENV-2." (PMID 32130369, 2020). "In the present study, we tested the effect of calpain I inhibitor ALLN and proteasome inhibitor MG132 on the sagB mutant infection-mediated GSK-3β degradation." (PMID 30926881, 2019). "Phospho-IκBα, NF-κB, phospho-β-catenin, and GSK3β phosphorylated at Y216, and proteins showed increased levels after infection, whereas unphosphorylated β-catenin and phospho-GSK3β at S9 were reduced." (PMID 31611869, 2019). "Secretion: T3S; targets: CRK, CRKL, PI3K subunits, and GSK3B; localization: cytosol, near the early vacuole; function: modulation of host gene expression related with immune signalling in early stages of infection." (PMID 31528632, 2019).